IAPP (islet amyloid polypeptide)
Diseases named in the same sentence as IAPP in open-access papers (continued):
Sharing a sentence is not in itself a finding about the gene and the disease.
type 2 diabetes (continued). "Type 2 diabetes mellitus is characterized by the abnormal accumulation of islet amyloid polypeptide (IAPP or amylin) in the islets of Langerhans." (PMID 30126231, 2018). "In type 2 diabetes, IAPP and insulin secretion is increased to compensate for decreased insulin sensitivity in peripheral tissues, leading to increased local IAPP concentrations and formation of islet amyloid deposits." (PMID 28500395, 2017). "Previously, we found that the serum protein C4b binding protein (C4BP) binds to human IAPP and co-localises to amyloid deposits in the pancreatic islets of individuals with type 2 diabetes." (PMID 28500395, 2017). "Accordingly, C4BP co-localises with IAPP amyloid in vivo in pancreatic islets from humans with type 2 diabetes." (PMID 28500395, 2017). "The human IAPP is extremely amyloidogenic in vitro, and amyloids accumulate in the pancreatic islet in the majority of the type II diabetes patients." (PMID 28261044, 2017). "For instance, overexpression of IAPP relative to insulin has been observed in rat models of type 2 diabetes, and TXNIP has been shown to inhibit insulin transcription while inducing IAPP transcription." (PMID 28980863, 2017). "Small oligomers formed early along human islet amyloid polypeptide (hIAPP) aggregation is responsible for the cell death in Type II diabetes." (PMID 27620620, 2016). "It inhibited the aggregation of islet amyloid polypeptide (IAPP), which is recognised to play a major role in the death of pancreatic β-islet cells in type II diabetes." (PMID 26891321, 2016). "These applications show that SFG can provide detailed information about structures, kinetics, and orientation of IAPP during interfacial aggregation, relevant to the molecular mechanisms of type II diabetes." (PMID 26697504, 2016). "Human islet amyloid polypeptide (hIAPP) is the major component of the amyloid deposits found in the pancreatic islets of patients with type 2 diabetes mellitus (T2DM)." (PMID 26636105, 2016). "Beyond this normal physiological role, IAPP has received much attention due to its possible involvement in the pathology of diabetes mellitus, or type II diabetes." (PMID 26649317, 2016). "In the current study, we investigated the feasibility of using an immunotherapeutic approach to target IAPP in a mouse model of type 2 diabetes." (PMID 27379014, 2016). "In type II diabetes, aggregation of this peptide into amyloid fibres is observed, and pre-amyloid states of IAPP are toxins resulting in β-cell death." (PMID 27108700, 2016). "The human islet amyloid polypeptide (hIAPP) is an intrinsically disordered protein that can self-assemble into fibrillar aggregates that play a key role in the pathogenesis of the type II diabetes mellitus." (PMID 27854243, 2016). "Type 2 diabetes mellitus is characterized by the deposition of islet amyloid polypeptide (IAPP) as amyloid in islets, a process thought to be toxic to β-cells." (PMID 27379014, 2016). "Recent work suggests a role for IAPP aggregation in cardiovascular complications of type-2 diabetes and hints at a possible role in type-1 diabetes." (PMID 26649319, 2016). "IAPP constitutes the main component of amyloid deposits found in the pancreas of type 2 diabetes mellitus patients." (PMID 27607147, 2016). "Insulin resistance and hyperglycemia characteristics of type 2 diabetes not only induce insulin production but also increase IAPP production, which demands higher concentrations of molecular chaperones to help with folding activities." (PMID 26960140, 2016). "They reported that isolated islets from these mice showed a marked reduction in amyloid accumulation upon a 2-week high glucose treatment; these conditions simulate the hyperglycemia observed in type II diabetes and stimulate IAPP expression and secretion." (PMID 26576436, 2015).
type 2 diabetes (continued). "The insulin-degrading enzyme (IDE) degrades amyloidogenic proteins such as Amyloid β (Αβ) and Islet Amyloid Polypeptide (IAPP), i.e. peptides associated with Alzheimer’s disease and type 2 diabetes, respectively." (PMID 26228656, 2015). "The major peptide constituent of the amyloid deposits in type 2 diabetes is islet amyloid polypeptide (IAPP)." (PMID 26191799, 2015). "Accelerated aggregation by ganglioside membranes has been observed for amyloid β (Aβ) from Alzheimer disease (AD) and islet amyloid polypeptide from diabetes type II (69, –, 71)." (PMID 25425650, 2015). "Delivery of NEP to peripheral tissues has also proved effective in reducing the deposits of islet amyloid polypeptide (IAPP) which contribute to type 2 diabetes." (PMID 25278875, 2014). "Even though IAPP and amyloid formation are much discussed in type 2 diabetes, our aim was to study the significance of IAPP in type 1 diabetes." (PMID 24671002, 2014). "It has not been fully understood how single amino acid sequence difference between hIAPP and rIAPP plays a role in the mechanical properties of IAPP fibrils related to their functional role in the expression of type II diabetes." (PMID 24551113, 2014). "Islet amyloid polypeptide (IAPP) aggregates into oligomers and form fibrils in the islets, and the amyloid deposits are associated with reduced β-cell mass in type 2 diabetic patients." (PMID 25503986, 2014). "A recent study has also identified phosphatidylethanolamine as a positive modulator of the membrane disruption induced by IAPP (islet amyloid polypeptide protein), an amyloidogenic protein involved in type II diabetes." (PMID 24086336, 2013). "One of the hallmarks of advanced type 2 diabetes is the development of amyloid plaques consisting of the endocrine hormone amylin (also known as islet amyloid polypeptide or IAPP)." (PMID 23457571, 2013). "IAPP is involved in glucose metabolism by interplaying with insulin and is found in amyloid deposits in the pancreas of type II diabetes patients." (PMID 23799448, 2013). "Inhibition of human islet amyloid polypeptide (hIAPP) fibrillisation by peptides incorporating a helicogenic amino acid, dehydrophenylalanine: implications for Type-2 diabetes." (PMID 23435449, 2013). "Human IAPP, islet amyloid deposits of which are found in type 2 diabetes, aggregates in the ECM and induces apoptosis and defects in insulin secretion." (PMID 22460761, 2012). "In the case of islet amyloid polypeptide/amylin (IAPP) involved in type II diabetes, EGCG inhibits amyloid formation when added to the lag phase and it has been shown to bind to intermediates as well as to monomers and mature fibers." (PMID 23242152, 2012). "Other proteins with an unordered structure are the IAPP in type II diabetes and β-amyloid in Alzheimer’s disease." (PMID 22350870, 2012). "For example, Islet amyloid polypeptide (IAPP) which is colocalized and secreted with insulin from β cell granules induces β cell apoptosis in cultured islets and in type 2 diabetes." (PMID 22474427, 2012). "Activation of the NLRP3 inflammasome by islet amyloid polypeptide has been also reported in type 2 diabetes." (PMID 22531291, 2012). "Recent research supports that aggregation of islet amyloid polypeptide (IAPP) leads to cell death and this makes islet amyloid a plausible cause for the reduction of beta cell mass, demonstrated in patients with type 2 diabetes." (PMID 21695120, 2011). "Some of the local forms of amyloid diseases are connected to severe maladies, such as type 2 diabetes where IAPP misfolds and deposits as amyloid in the islet of Langerhans, and Alzheimer's disease where the Aβ protein is deposited in the CNS." (PMID 21695120, 2011).
type 2 diabetes (continued). "Amyloid deposits in the islets of Langerhans are a pathologicalcharacteristic of type 2 diabetes, and the amyloid aggregates consist of isletamyloid polypeptide (IAPP)." (PMID 18566681, 2008). "Human islet amyloid polypeptide (hIAPP), a pancreatic islet protein of 37 amino acids, is the main component of islet amyloid, seen at autopsy in patients with type 2 diabetes mellitus (DM2)." (PMID 18497871, 2008). "As other amyloid-relatedproteins and polypeptides, the IAPP identified in these deposits is thewild-type polypeptide in most type II diabetes cases." (PMID 18566678, 2008). "The presence of fibrillar protein deposits (amyloid) of human islet amyloid polypeptide (hIAPP) in the pancreatic islets of Langerhans is thought to be related to death of the insulin-producing islet β-cells in type 2 diabetes mellitus (DM2)." (PMID 18483616, 2008). "The formation of amyloid deposits by IAPP appears to play a central role in the pathogenesisof type II diabetes." (PMID 18566678, 2008). "We also examined the OC staining of islet amyloid deposits in the pancreas of human IAPP transgenic mouse model of type II diabetes." (PMID 17897471, 2007). "Nonetheless, IAPP is mainly known as the major component of the amyloid fibrils observed in the pancreatic islets of patients afflicted with type 2 diabetes, and the accumulation of these insoluble protein deposits correlates closely with the loss of pancreatic β-cells." (PMID 41898461, 2026). "Here, we have extended this approach toward type II diabetes by assessing the efficacy of the CPP construct, designated as neural cell adhesion molecule-1 (NCAM1)-prion protein (PrP), in inhibiting IAPP oligomerization, fiber formation, and associated cytotoxicity." (PMID 41926749, 2026). "The heterologous seeding between IAPP and Aβ shown here may represent a molecular link between type 2 diabetes and AD." (PMID 40305318, 2025). "IAPP influences the development and progression of both type 2 diabetes and AD." (PMID 39770025, 2024). "Misfolded IAPP produced in type 2 diabetes may potentiate AD pathology by cross-seeding Aβ, providing a molecular explanation for the link between these diseases." (PMID 39770025, 2024). "While a variety of mechanismsmay ultimately be responsible for the onset of type 2 diabetes underthese circumstances, one mechanism that has been postulated involvesthe increased aggregation of human islet amyloid polypeptide (hIAPP)through direct interaction with SARS-CoV-2 viral proteins." (PMID 39582236, 2024). "Therefore, IAPP is an important pathological factor that causes type 2 diabetes mellitus (T2DM)." (PMID 37249284, 2023). "When the potential therapeutic use of FeTPPS in type 2 diabetes to improve the pancreatic β-cell dysfunction was explored, this metalloporphyrin significantly attenuated the cytotoxicity induced by human islet amyloid polypeptide (hIAPP) in a dose-dependent mode." (PMID 37372002, 2023). "However, oligomeric and fibrillar forms of IAPP are related with pathological conditions, such as type 2 diabetes mellitus (T2DM)." (PMID 36793056, 2023). "Thesenew insights into the mechanism of IAPP aggregation on membranes mayhelp to understand IAPP toxicity and will be important for the developmentof therapeutics to prevent β-cell death in type II diabetes." (PMID 35749314, 2022). "It is well known that the toxic amyloid-like aggregates of β-amyloid (APP), tau (MAPT), α-synuclein (SNCA or PARK1), and islet amyloid polypeptide (IAPP) are linked with neurodegeneration in Alzheimer’s disease (AD), frontotemporal dementia (FTD), Parkinson’s disease (PD) or Type 2 diabetes (T2D)." (PMID 35565658, 2022). "Consequently, inhibition of IAPP fibrillation to minimize β-cell cytotoxicity is an important approach towards β-cell preservation and type 2 diabetes management." (PMID 35216095, 2022).
type 2 diabetes (continued). "The IDP class includes the β-amyloid peptide (Aβ) as one of the sequential proteolysis products of amyloid precursor protein (APP) in Alzheimer’s disease (AD), tau protein in AD and other tauopathies, α-synuclein in Parkinson’s disease (PD), and islet amyloid polypeptide (IAPP) in type II diabetes." (PMID 35646824, 2022). "Inhibition of IAPP toxicity is a potential therapeutic target in type 2 diabetes." (PMID 34554282, 2022). "Type 2 Diabetes involves a peptide called human islet amyloid polypeptide (hIAPP), which undergoes a conformational change, triggering the aggregation process leading to amyloid aggregates and fibers rich in β-sheets mainly found in the pancreas of all diabetic patients." (PMID 34604227, 2021). "Human islet amyloid polypeptide (hIAPP, involved in type II diabetes) spontaneously undergoes liquid–liquid phase separation (LLPS) and a kinetically complex hydrogelation, both catalysed by hydrophobic–hydrophilic interfaces (e.g. air–water interface and/or phospholipids–water interfaces)." (PMID 34313292, 2021). "As a recent example, a therapeutic Qβ-based VLP displaying islet amyloid polypeptide (IAPP) on its surface was able to induce potent antibodies against IAPP aggregates in islets of vaccinated mice, causing a delayed onset of type II diabetes in this murine disease model." (PMID 35126381, 2021). "Likewise, early oligomerization of IAPP is responsible for β-cell death in the pancreas in Type II diabetes." (PMID 34883675, 2021). "IAPP has been proven to play a role in the activation of macrophages through IL-1, and inflammatory cascades are triggered by the uptake of IAPP aggregates by macrophages in type 2 diabetes." (PMID 33221741, 2020). "IAPP deposition in the brain of type-2 diabetes patients with dementia and patients with AD led to the hypothesis that IAPP along with Aβ is involved in AD pathology." (PMID 31947546, 2020). "In type 2 diabetes patients, IAPP forms cytotoxic ‘amyloid’ plaques within islets." (PMID 31796987, 2020). "Islet amyloid polypeptide (IAPP) form β-sheet aggregates in the pancreas in type 2 diabetes." (PMID 30542277, 2018). "We see that IAPP down-regulates both mitochondrial thioredoxin dependent peroxide reductase and peroxiredoxin 1, thus potentially explaining how oxidative stress is increased in type 2 diabetes." (PMID 30419808, 2018). "Human islet amyloid polypeptide (hIAPP) is a naturally occurring, intrinsically disordered protein whose abnormal aggregation into amyloid fibrils is a pathological feature in type 2 diabetes, and its cross-aggregation with amyloid beta has been linked to an increased risk of Alzheimer’s disease." (PMID 30149632, 2018). "The reversal of any of these effects, perhaps by targeting proteins which alter in response to IAPP, may be beneficial for type II diabetes." (PMID 30419808, 2018). "A tandem mass spectrometry based label free approach, combined with OFFGELTM fractionation at the protein level, was used here to investigate the effects of human IAPP aggregation on the proteome of rat pancreatic insulinoma Rin-5F cells, a cell line widely used in studies of type 2 diabetes." (PMID 30419808, 2018). "In pancreatic sections from individuals with type 2 diabetes, islets with amyloid deposits contained significantly more macrophages than those without, reflecting the association between IAPP, macrophages and inflammation." (PMID 28500395, 2017). "Aggregation of islet amyloid polypeptide (IAPP), a peptide hormone co-synthesized and co-stored with insulin in pancreatic cells and also co-secreted to the circulation, is associated with beta-cell death in type-2 diabetes (T2D)." (PMID 28550295, 2017). "Besides insulin resistance, type 2 diabetes is characterized by a deficit in β-cell mass as a result of misfolded human islet amyloid polypeptide (h-IAPP) which forms toxic aggregates that destroy pancreatic β-cells." (PMID 26960140, 2016).
type 2 diabetes (continued). "Thus, the idea of using immunotherapy to clear or prevent IAPP deposits seen in type 2 diabetes holds considerable promise as a therapeutic strategy." (PMID 27379014, 2016). "Islet amyloid polypeptide (IAPP) is a peptide central to β-cell pathology in type II diabetes." (PMID 27108700, 2016). "Although IAPP amyloid aggregates are not the cause of type 2 diabetes, they are associated with loss of mass and function of β-cells." (PMID 27607147, 2016). "As IAPP aggregates are a prominent feature of type 2 diabetes that may be involved in its pathogenesis, targeting these for clearance is an attractive approach." (PMID 27379014, 2016). "In conclusion, IAPP targeting immunotherapy may have benefits in humans suffering from type 2 diabetes." (PMID 27379014, 2016). "By this definition, fewer than 25 amyloid-forming proteins have been identified and associated with serious diseases, including amyloid-β peptide (Aβ) with Alzheimer's disease (AD), islet amyloid polypeptide (IAPP) with diabetes type 2, and prion protein (PrP) with the spongiform encephalopathies." (PMID 27051538, 2016). "Human IAPP (hIAPP), but not rodent IAPP (rIAPP), forms oligomers and fibrils leading to the amyloid deposits associated with type 2 diabetes." (PMID 26191799, 2015). "Besides, the capacity of similar aggregates, such as islet amyloid polypeptide (IAPP) in type II diabetes, to activate NLRP3 inflammasome via abnormal phagocytosis and lysosomal rupture mechanism has also been shown." (PMID 26091541, 2015). "IAPP is natively unstructured but gains α-helical structure upon binding to anionic membranes and forms β-sheet-rich amyloid fibers during the progression of type II diabetes." (PMID 26582441, 2015). "However, considering that pancreatic islets from patients afflicted with type II diabetes are almost all converted into amyloids, this massive IAPP deposition most likely interferes with normal β-cell functions, such as insulin release." (PMID 26576436, 2015). "Masters and colleagues demonstrated that soluble oligomers of islet amyloid polypeptide (IAPP), a protein that forms amyloid deposits in the pancreas during type 2 diabetes, could be endocytosed and trigger the NLRP3 inflammasome and generate mature IL-1β." (PMID 23762269, 2013). "Indeed, the 37-residue long human form of IAPP is the major protein constituent of pancreatic islet amyloid deposits found in 95% of Type 2 Diabetes (T2D) patients." (PMID 24009497, 2013). "IAPP can, however, also play a pathological role, contributing to Type II diabetes (T2D)." (PMID 24009497, 2013). "In addition, the beta cell secretome is altered in individuals with type 2 diabetes, for example, it displays increased amounts of proinsulin and augmented levels of human islet amyloid polypeptide (IAPP) (which is co-secreted with insulin)." (PMID 22460761, 2012). "Although the initial definition of amyloid was extracellular deposition of proteinaceous fibrillar material, the use of the term has changed as more evidence exists on the presence of intracellular aggregates of i.e. Aβ in AD and islet amyloid polypeptide-derived amyloid in type II diabetes." (PMID 21179560, 2010). "Notably, IAPP has been shown to induce the formation of α‐Syn aggregates in vitro, which may explain why patients with type II diabetes are more likely to develop PD." (PMID 40599234, 2025). "Therefore, targeting IAPP could prove to be beneficial not only for managing type II diabetes but also for potentially treating or even preventing AD." (PMID 38440398, 2024). "This study therefore identifies IAPP oligomers as an important target for drug discovery for diabetes type II, and indicates that the design of inhibitors of secondary nucleation could be developed as a treatment to preserve or restore the function of β-cells in this disease." (PMID 34790701, 2021). "In type 2 diabetes mellitus (T2DM), the accumulation of the islet amyloid polypeptide (IAPP), also termed amylin, is observed." (PMID 32210005, 2020).